PAX7 (paired box 7)
Diseases named in the same sentence as PAX7 in open-access papers (continued):
Sharing a sentence is not in itself a finding about the gene and the disease.
cancer (47 papers, 2010 to 2026). A tumor composed of atypical neoplastic, often pleomorphic cells that invade other tissues. "Anomalous PAX7 levels have been linked to several types of cancer, particularly rhabdomyosarcoma, where the fusion of the PAX7 gene with the FOX01 gene (known as the PAX7‐FOXO1 fusion gene) is a frequent genetic occurrence." (PMID 40370330, 2025). "In accordance with our findings, a severe muscle regeneration defect was associated with an elevated number of Pax7-positive satellite cells in a cancer cachexia model using colon-26 (C26) cancer cells." (PMID 35994202, 2022). "Increased PAX7 expression sustains local inflammation in muscles of cachectic mice and underlies impaired muscle regeneration during cancer cachexia." (PMID 32824440, 2020). "Here we show that the impairment of muscle regeneration after local damage in cancer cachexia is associated with a prolonged inflammation and increased Pax7 expression." (PMID 27034684, 2016). "Notably, PAX7 has recently been implicated in maintaining cancer stemness by activating Wnt/β‐catenin and Notch pathways, thereby enriching chemotherapy‐resistant subpopulations in triple‐negative breast cancer." (PMID 41532150, 2026). "For example, we found that muscle-related functions were enriched in phase-separating protein-coding genes, while previous studies supported that cancer may cause muscle loss by overexpression of Pax7, and the Pax7 protein was also predicted to be a phase-separating protein in this study." (PMID 41154723, 2025). "One promising area of research is the PAX7 gene, which has shown a vital role in the progression of several cancer types." (PMID 41532150, 2026). "Examination of RNA‐seq information from the TCGA repository revealed variations in PAX7 expression among various cancer types, showing increased levels in BRCA, LUAD, LUSC, STAD, and THCA, while decreased levels were noted in PRAD and GBM." (PMID 40370330, 2025). "The Transwell study indicated a reduction in the invasive and migratory capabilities of cancer cells following the suppression of PAX7." (PMID 40370330, 2025). "PAX7 knockdown affected over 2000 genes and inhibited cancer cell proliferation, migration, and invasion, involving the Wnt/β‐catenin pathway." (PMID 40370330, 2025). "PAX7, as a transcription factor, has been implicated in EMT, a critical process for cancer cell migration and invasion." (PMID 41200166, 2025). "Suppression of PAX7 hindered the growth, movement, and infiltration of cells, highlighting its importance in the behaviour of cancer cells." (PMID 40370330, 2025). "We utilised Kaplan–Meier analysis to investigate how PAX7 expression correlates with the prognosis of the mentioned cancers." (PMID 40370330, 2025). "The enhanced expression of PAX3 or PAX7 in ARMS–here as a fusion protein–is reminiscent of MuSCs in cancer cachexia which are also displaying aberrant high levels of Pax7 expression." (PMID 39050890, 2024). "It has been observed that PAX7 upregulation exacerbates muscle mass decline and increases muscle wasting in cancer cachexia, while inhibition of NF-κB signaling rescues cancer-related atrophy." (PMID 39062745, 2024). "It was demonstrated that cancer leads to an overactivation of NF-κB signaling, leading to a Pax7-dependent down-regulation of MyoD." (PMID 33718372, 2021). "Skeletal muscle in PDX mouse cancer models also shows reduced regenerative capacity due to dysregulation of Pax7." (PMID 31941005, 2020). "In atrophying muscles, NF-κB overactivation in turn leads also to abnormal accumulation of PAX7, a transcription factor driving muscle regeneration in normal circumstances but failing to do so during cancer cachexia." (PMID 32824440, 2020). "The significance of muscle precursor cells and the cancer-induced impairment of the differentiation program, as modulated by Pax7, comprise an area of interest and are left to future work." (PMID 32605273, 2020).
cancer (continued). "The overexpression of muscle stem cell factor PAX7 prevents cell differentiation and promotes cancer induced muscle wasting." (PMID 31028132, 2019). "Physiological Pax7 expression drives myogenic stem cell commitment, while its persistent expression in cancer cachexia has been shown to inhibit the differentiation of muscle stem cell." (PMID 27034684, 2016). "In summary, here we demonstrate that, in addition to the already known beneficial effects in cancer patients, physical activity downregulates Pax7 and restores muscle mass by increasing glycolytic fiber size." (PMID 27034684, 2016). "Previous studies on cancer-related muscle wasting performed in C26-bearing mice showed a strong reduction of the myogenic potential of muscle stem cells in a Pax7-dependent manner." (PMID 27034684, 2016). "In vivo, cancer cachexia results in increased number of Pax7+ cells that also express C/EBPβ and the inhibition of normal repair mechanisms." (PMID 26709824, 2015). "Taken together, these results suggest that cancer cachexia increases the Pax7+ compartment size and these cells have increased expression of C/EBPβ but reduced regenerative capabilities." (PMID 26709824, 2015). "PAX7 was highly expressed in cancer tissues and had a notable impact on patient survival." (PMID 41532150, 2026). "The clone formation experiment showed that the knockdown of PAX7 could reduce the clone formation of cancer cells." (PMID 40370330, 2025). "Transwell experiments showed that SKL2001 could reverse the inhibitory effect of knocking down PAX7 on cancer cell migration and invasion." (PMID 40370330, 2025). "Inhibition of PAX7 disrupts cancer cell proliferation and metastasis." (PMID 40370330, 2025). "RNA‐seq data from the TCGA database assessed PAX7 expression across cancer types." (PMID 40370330, 2025). "The aberrant expression of Pax7 or Pax3 might be one of the main drivers of impaired myogenic differentiation in ARMS as observed in MuSCs in cancer cachexia." (PMID 39050890, 2024). "Thus, miR-486 is an integral part of the myogenesis signaling network that involves Pax7, MyoD, myostatin, and NF-κB and a potential target of cancer-induced chemokines/cytokines." (PMID 31941005, 2020). "The PAX7 gene play critical roles during fetal development and cancer growth." (PMID 32272578, 2020). "Indeed, persistent expression of the self-renewal factor Pax7 was shown in in vivo and in vitro models of cancer cachexia in previous investigations." (PMID 33142912, 2020). "Furthermore, in a mouse model of cancer cachexia, PAX7 protein is highly upregulated, which suppresses myogenic differentiation of satellite cells, leading to muscle atrophy." (PMID 30139390, 2018). "We recently showed that NF-kB-induced Pax7 overexpression impairs the myogenic potential of muscle precursors in cachectic mice, suggesting that lowering Pax7 expression may be beneficial in cancer cachexia." (PMID 27034684, 2016). "Furthermore, we propose voluntary exercise as a physiological tool to counteract the overexpression of Pax7 observed in cancer cachexia." (PMID 27034684, 2016). "Increased Pax7 and decreased myogenin levels have been reported also in the cachectic muscle of mice bearing the C26 carcinoma and in cancer patients, opening the possibility that cancer-driven inflammation induces muscle atrophy, dysregulating SC differentiation program." (PMID 26508819, 2015). "The authors wish to thank Dr. Stephen Lee for SKOV3, MCF7, A549 and HCT116 human cancer cells, Dr. Esta Sterneck for the C/EBPβ floxed mouse, Dr. Charles Keller for the Pax7-CreERtm mouse, Dr. Robert Korneluk for critical reading of this manuscript, Dr. Bernard Jasmin for guidance." (PMID 26709824, 2015). "This phenomenon is exemplified here for two private cases: PAX7, a homeodomain transcription factor that plays important roles during fetal development and cancer growth, and KITLG, a ligand of the KIT tyrosine-kinase receptor, which acts in cellular development." (PMID 22096567, 2011).
cancer (continued). "Given that PAX7 is among the earliest genes involved in neural progenitor commitment in the embryo, the elevated expression of PAX7 in PTEN-deficient GSCs may account for the low-differentiated histology of GBM, a common feature for more aggressive cancers." (PMID 26632666, 2015). "We also found that these cells express unique markers like PAX7 (paired box 7) and CHODL (chondrolectin), which can potentially be used to identify these cells in human cancers." (PMID 38273014, 2024). "XAF1, TRIM31, G0S2 and IFI6 have known roles in apoptosis or its prevention, while PAX7, TRIM31 and PNMA8A are involved in cell development/development of cancer." (PMID 38990812, 2024). "The region contains multiple genes with a known or suspected role in cancer including ARID1A, E2F2, NBPF1, PAX7, RUNX3 and SDHB." (PMID 25420937, 2014). "However, a substantial number of Pax7+ cells were found in the dystrophic muscle interstitium, similar to what has been previously shown in DMD patient muscle and murine cancer cachexia." (PMID 36278481, 2022). "Selected candidate genes, i.e., UBASH3A, MYH13, UTP11L, and PAX7, were further evaluated using protein expression analysis but no alterations of cancer-related pathways were observed." (PMID 35625741, 2022). "It was not feasible to enumerate the population of Pax7–/MyoD+ cells in response to the xenografted cancer or WFA treatment due to experimental limitations." (PMID 33718372, 2021). "Therefore, there is an intricate signaling network with feed-forward and feedback loops comprising of NF-κB, PAX7, MyoD, myostatin, miR-486, and MMP-9 that regulate skeletal muscle homeostasis, which is disrupted in cancer." (PMID 31941005, 2020). "Collectively, TNF-α seemed not to be a cytokine suppressing Pax7 and myogenic differentiation in cancer cachexia." (PMID 30300394, 2018). "As a control, we included transcription factor Pax7, which is not intended to play a role in megakaryocyte development but is indicated in fetal development and cancer growth." (PMID 28572580, 2017). "In addition, we evaluated glycolytic fibers areas, which are highly reduced in cancer-related muscle atrophy but not after exercise-induced Pax7 downregulation." (PMID 27034684, 2016).
infection (13 papers, 2004 to 2025). The state of being infected such as from the introduction of a foreign agent such as serum, vaccine, antigenic substance or organism. "Western blotting of cell lysates confirmed that infection of cells with Pax3 or Pax7 RV resulted in an increase in MyoD protein, whereas infection with retroviruses encoding Pax3DN or Pax7DN resulted in a decrease in MyoD protein." (PMID 19221588, 2009). "Notably, infection of Pax7-deficient muscle with adenoviral Pax7 resulted in the de novo formation of regenerated myofibers." (PMID 15138500, 2004). "Compared to sh-NC, sh-DGAT2 infection of BSCs significantly inhibited the mRNA expression of PAX7, MYOD1, MYOG, and MYR4 (p < 0.05)." (PMID 35883393, 2022). "Immunophenotyping of skeletal muscle cells at initial stage of infection - Immunofluorescence assay of skeletal muscle at 48 hpi showed that the first cells to appear infected were Pax7+ (orange arrows)." (PMID 31826129, 2019). "In the present study, we demonstrated that chicken skeletal muscle cells are susceptible to in vitro infection by YF17DD virus, and that Pax7 positive cells play a central role in muscle infection both in vivo and in vitro." (PMID 31826129, 2019). "Some Pax7-positive cells were also found positive for SDV antigens at 26 days post-infection, thus demonstrating that SDV exhibits a particular tropism for rainbow trout satellite cells." (PMID 26743565, 2016). "By contrast, infection of regenerating Pax7 −/− TA with Ad-Pax7 resulted in the generation of an average of 192 myofibers." (PMID 15138500, 2004). "Infection of CD45+:Sca1+ cells from uninjured muscle with retrovirus expressing Pax7 efficiently activated the myogenic program." (PMID 15138500, 2004). "Infection of Pax7 −/− CD45+:Sca1+ cells with Pax7 retrovirus resulted in high levels of retroviral Pax7 transcript but no expression of Myf5 mRNA by Northern blot hybridization or RT-PCR (data not shown)." (PMID 15138500, 2004). "After infection, we obtained two groups, overexpressing Pax3 and Pax7 (mark as OEPax3 and OEPax7)." (PMID 33336498, 2021). "It is therefore likely that in adult muscle progenitor cells, there is significant overlap between Pax3 and Pax7 target gene selection, explaining the similar outcomes of infection with Pax3 and Pax7 RV and of inhibiting target gene transcription using the dominant-negative versions." (PMID 19221588, 2009). "Infection of CD45−:Sca1− cells from Pax7 −/− muscle similarly gave rise to myoblasts." (PMID 15138500, 2004). "A MuSC clone that expressed both Pax7-GFP reporter and MyoG-mCherry reporter post-infection in a hydrogel microwell was readily visualized by fluorescent time lapse microscopy." (PMID 36639373, 2023). "The reduction of Ki67+ Pax7+ cells suggested that there was no activation and proliferation of satellite cells after EV-D68 infection of 3D TESMs." (PMID 40912913, 2025). "Also upregulated are PAX7, MYOG, and MYF5, all classic markers of myogenic differentiation and regeneration, indicating either inappropriate activation of muscle-lineage genes or potential cellular stress responses induced by prolonged infection." (PMID 40863220, 2025). "In contrast to the ability of ectopic PAX3-FOXO1A, Pax3 and Pax7 were unable to induce each other, or myogenic proteins, in NIH 3T3 fibroblasts maintained under expansion conditions (although specific culture conditions can produce limited activation of the myogenic program after Pax3 infection)." (PMID 19221588, 2009). "Infection of C2C12 cells or satellite cell-derived myoblasts with Pax3 RV or Pax7 RV did not prevent the development of multinucleate myotubes, though in both cases there was a slight delay (∼24 h) in fusion." (PMID 19221588, 2009).
myopathy (10 papers, 2015 to 2026). A disease of the muscle in which the muscle fibers do not function properly. "Recently, pathogenic variants in PAX7, the master transcriptional regulator of muscle stem cells, have been associated with myopathies of variable severity, arguing for impaired satellite cell function as the main pathogenic driver." (PMID 41611663, 2026). "Among the downregulated genes, PAX7 encoding a transcription factor is required for neural crest formation and biallelic variants in which are a genetic cause of myopathy characterized by hypotonia." (PMID 39521780, 2024). "Considering its central role in satellite cell specification and function, it is unsurprising that mutations in the transcription factor PAX7 cause a myopathy." (PMID 34740639, 2022). "A higher level of PAX3 expression was also observed in the muscles of patients carrying loss of function mutation in PAX7 gene, leading to a myopathy of variable severity." (PMID 32552916, 2020). "Notably, patients affected with JAG2-myopathy also display severe reduction of PAX7, concomitant with reduced expression of its target gene MYF5, suggesting a dysfunctional satellite cell niche." (PMID 34740639, 2022). "Based on these results and the fact that multiple progenitor populations can contribute to muscle regeneration after myopathy, including Pax7+ satellite cells and NG2+ pericytes, we next examined the myogenic potential of Ang-1 and MC CM in co-cultures of pluripotent cells." (PMID 26042050, 2015). "Indeed, Fc-TWEAK may have affected the expression of the shared aberrantly expressed genes identified with the myogenesis, myopathy, and glucose metabolism PCR arrays such as Pax7 and Titin as well as the pathways (e.g. MAPK and AMPK)." (PMID 35902978, 2022). "Structural muscle genes (ACTA1, TTN) were reduced to levels similar to those in DM, while markers of muscle regeneration (NCAM1, PAX7, MYH3, MYH8) were only mildly increased compared to normal muscle, and lower than in other inflammatory myopathies." (PMID 41441888, 2025). "Given the myopathic changes in Mbnl1−/−/Mbnl2+/− mice, and the lack of significant myopathy or changes in Pax7 expression and MuSCs in the individual knockout lines, we decided to evaluate the Mbnl1−/−/Mbnl2+/− mice for these parameters." (PMID 38473933, 2024). "This, coupled with the absence of a regeneration response driven by an increase in PAX7, MYOD1 and myogenin, apparently cause the slow, progressive myopathy observed in Sil1Gt mice." (PMID 29666155, 2018). "Interestingly, the induction of SYT-SSX expression through Hprt-Cre, Pax3-Cre, or Pax7-Cre resulted in embryonic lethality, and SYT-SSX expression in Myf6-expressing myocytes or Myf6-expressing myofibers resulted in myopathy but no tumors." (PMID 27191748, 2017).
skeletal muscle disorder (2 papers, 2017 to 2024). A disease involving the skeletal muscle tissue. "Additionally, MLPA analysis of the PAX7 gene, which encodes a transcription factor involved in muscle stem cell proliferation and myogenesis and is associated with skeletal muscle disorders, was also performed." (PMID 39766922, 2024).
adenocarcinoma (1 paper, 2024). A common cancer characterized by the presence of malignant glandular cells.
neurological disorders (1 paper, 2020). "Pax7 was shown to play a role in the development of the central nervous system, and Pax7-null mice are characterized by many neurological disorders." (PMID 32552916, 2020).
PAX7 also shares sentences with these, for which no sentence is quoted: colon cancer (3 papers); leukemia (3); myocardial infarction (2); acute lymphoblastic leukemia (1); acute myeloid leukemia (1); Arthritis (1); colorectal cancer (1); congenital muscular dystrophy (1); epilepsy (1); Erythema (1); Failure to thrive (1); frontonasal dysplasia (1); gastric adenocarcinoma (1); hematological malignancies (1); hepatoblastoma (1); Hyperinsulinemia (1); hypogonadism (1); infiltrating ductal carcinoma (1); inflammation (1); Insulin resistance (1); liposarcoma (1); lung adenocarcinoma (1); lung squamous cell carcinoma (1); lymph node metastasis (1); lymphedema (1); neurodegenerative disease (1); ovarian carcinoma (1); Parkinson disease (1); premature ovarian failure (1); prostate adenocarcinoma (1).
A further 7 diseases each share a sentence with PAX7 in 1 paper.